PAK1IP1 (PAK1 interacting protein 1)
Description:
Negatively regulates the PAK1 kinase. PAK1 is a member of the PAK kinase family, which has been shown to play a positive role in the regulation of signaling pathways involving MAPK8 and RELA. PAK1 exists as an inactive homodimer, which is activated by binding of small GTPases such as CDC42 to an N-terminal regulatory domain. PAK1IP1 also binds to the N-terminus of PAK1, and inhibits the specific activation of PAK1 by CDC42. May be involved in ribosomal large subunit assembly.
Synonyms: hPIP1; PIP1; WDR84; FLJ20624; bA421M1.5; MAK11
Tractability: PROTAC: ubiquitination databases record sites on it; its protein half-life has been measured.
Gene: Protein-coding gene on chromosome 6 (10,694,633 to 10,711,166, forward strand). Ensembl gene ENSG00000111845.
Subcellular location: Nucleus, nucleolus
Subcellular location (Human Protein Atlas): Nucleoli
Gene Ontology:
Molecular function: protein binding; protein kinase inhibitor activity
Biological process: ribosomal large subunit biogenesis; maturation of LSU-rRNA from tricistronic rRNA transcript (SSU-rRNA, 5.8S rRNA, LSU-rRNA)
Cellular component: nucleolus
Genetic constraint (gnomAD): Loss-of-function variants: 13 observed, 16.2 expected, observed/expected ratio (o/e) 0.8, 90% interval 0.52 to 1.28. The upper end of that interval is the gene's LOEUF score, 1.28, which puts it in group 5 of 6, group 1 being the genes least tolerant of losing a copy. Missense variants: 232 observed, 276.72 expected, observed/expected ratio (o/e) 0.84, 90% interval 0.75 to 0.94. Synonymous variants: 88 observed, 93.89 expected, observed/expected ratio (o/e) 0.94, 90% interval 0.79 to 1.12.
Homologues: Orthologues: chimpanzee PAK1IP1 (99% identical), macaque PAK1IP1 (90% identical), dog PAK1IP1 (84% identical), rabbit PAK1IP1 (83% identical), guinea pig PAK1IP1 (77% identical), pig PAK1IP1 (76% identical), rat Tmem14c (75% identical), mouse Pak1ip1 (72% identical), zebrafish pak1ip1 (52% identical), Drosophila melanogaster CG12608 (30% identical). Paralogues in human: MAPKBP1 (19% identical), WDR7 (18% identical), WDR62 (17% identical), TEP1 (16% identical), PAFAH1B1 (15% identical), AHI1 (14% identical), SNRNP40 (14% identical), WDR81 (14% identical), POC1A (13% identical), WDR5 (13% identical), WDR17 (13% identical), WDR43 (13% identical), and 14 more.
Diseases named in the same sentence as PAK1IP1 in open-access papers:
PAK1IP1 is named in the same sentence as 6 diseases in open-access papers, as found by Europe PMC text mining. Sharing a sentence is not in itself a finding about the gene and the disease. The quoted sentences say what the papers report.
cleft lip (1 paper, 2013). Congenital defect in the upper lip where the maxillary prominence fails to merge with the merged medial nasal prominences. "The possible role for PAK1IP1 (6p24.2) in human disease was suggested by studies mapping translocation breaking points associated with cleft lip and palate in affected individuals to human chromosome 6p24.1." (PMID 23935987, 2013).
orofacial clefting (1 paper, 2013). "Our findings prompted us to examine human cases of orofacial clefting for mutations in the PAK1IP1 gene or association with the locus." (PMID 23935987, 2013). "No deleterious variants in the PAK1IP1 gene coding region were recognized, however, we identified a borderline association effect for SNP rs494723 suggesting a possible role for the PAK1IP1 gene in human orofacial clefting." (PMID 23935987, 2013).
retinal disease (1 paper, 2017). "According the paper, among these DEGs, PTPRG, CSPG5 and NAV3 are at loci associated with retinal disease; MFAP3L, CSPG5 and PAK1IP1 locate in the regions carrying SNP's significantly associated with AMD." (PMID 28924976, 2017).
cancer (3 papers, 2021 to 2024). A tumor composed of atypical neoplastic, often pleomorphic cells that invade other tissues.
tumor (2 papers, 2013 to 2021). "The heatmap showed that 12 tumor suppressors formed into two clusters: cluster 1 contains seven downregulated tumor suppressors including PTEN, PSME1, DNAJB1, HSPH1, DEDD2, PAK1IP1, and MIR1244-3; and cluster 2 contains five upregulated tumor suppressors (OSGIN1, IFI27L1, MTCH2, NKD2, and IBTK)." (PMID 34571936, 2021).
PAK1IP1 also shares sentences with these, for which no sentence is quoted: gastric cancer (1 paper).